IL10 (interleukin 10)
Diseases named in the same sentence as IL10 in open-access papers (continued):
Sharing a sentence is not in itself a finding about the gene and the disease.
schizophrenia (continued). "Peripheral IL-10 did not alter the abnormalities of WM in patients but peripheral IL-10 was related to WM integrity, indicating that the peripheral IL-10 may play a regulatory role in the disruption of microstructural WM integrity and the pathogenesis of schizophrenia." (PMID 30792621, 2019). "The two variations that we genotyped gave us an interaction model of heterozygous, and IL10 and DBH have been identified to influence negative and positive symptoms of schizophrenia, respectively." (PMID 23951054, 2013). "However, induced secretion of CXCL8 (but not IL-10), i.e., the ratio of PHA-stimulated to non-stimulated secretion, increased significantly in the schizophrenia group." (PMID 35782435, 2022).
enterocolitis (88 papers, 2008 to 2026). An inflammatory process affecting the small intestine and colon. "The same group subsequently employed SMA or portal vein delivery of AAV10 vectors encoding the murine IL10 gene under the CBA promoter in IL10−/− mice (a model of enterocolitis)." (PMID 41463087, 2025). "In earlier studies that evaluated the role of IL-10 deficiency on the development of enterocolitis, a widely divergent disease susceptibility was found that was entirely dependent upon genetic background." (PMID 40671790, 2025). "Initial studies in IL-10-deficient mice showed the role of IL-10 in suppressing antigen-presenting cell function, given that mutants exhibited excessive bacteria-induced IL-12 production and developed enterocolitis." (PMID 41194916, 2025). "Humans with deleterious mutations in IL-10 or IL-10R present with severe, life-threatening enterocolitis within the first few months of life." (PMID 38383790, 2024). "For example, in a murine model of enterocolitis (manifested by loss IL-10), experimental enterocolitis was less severe with cGAS-deficiency and was completely abrogated with STING-deficiency." (PMID 38881893, 2024). "Children with mutations in Il-10, Il-10RA and Il-10RB genes manifested with severe enterocolitis with perianal lesions and penetrating behavior within first months of life." (PMID 38137450, 2023). "In this sense, mice deficient in interleukin 10 (IL-10−/−) spontaneously develop enterocolitis under conventional housing conditions after 12 weeks of age, which is then used as a model of IBD." (PMID 37373041, 2023). "This is supported by the findings that Il-10−/− and IL-10 receptor b null (Ilbrb−/−) mice develop spontaneous enterocolitis, and that polymorphisms in IL-10R and IL-10 are associated with UC in early childhood." (PMID 36519841, 2023). "Mice with IL-10 deficiency harbor intestinal microflora and trigger an enterocolitis in developing neonates." (PMID 36430939, 2022). "While most childhood IBD cases are polygenic in nature, many children with VEO-IBD have an underlying monogenetic disorder that results in severe enterocolitis, including mutations in IL-10 and/or IL-10R." (PMID 36012618, 2022). "Other pathological lesions of enterocolitis in Il-10 deficient mice are as follows epithelial hyperplasia, mucin depletion, crypt abscesses, ulcers, and thickening of bowel wall." (PMID 33691712, 2021). "IL-10 was first found to have immuno-regulatory effects in the intestine upon the discovery of spontaneous enterocolitis in IL-10-deficient mice." (PMID 30718924, 2019). "The development of spontaneous enterocolitis in mice deficient for IL-10 and IL-10Rβ has demonstrated the crucial role of IL-10 in maintaining the integrity of the intestinal epithelium." (PMID 30640950, 2019). "Enterocolitis was a reality in mutant mice unable to express the IL-10 and this chronic inflammation was linked to an uncontrolled immune response to a variety of antigens present in the enteric lumen." (PMID 32118051, 2019). "The role of IL-10 in intestinal inflammation is also seen in the mouse model, as IL-10-deficient mice develop microbiome-dependent spontaneous enterocolitis." (PMID 29545807, 2018). "To address this, we applied Nod2-deficient IL-10−/− (Nod2−/− IL-10−/−) mice and IL-10−/− counterparts both with a depleted intestinal microbiota to warrant pathogen-induced enterocolitis." (PMID 28752081, 2017). "IL-10 is an essential anti-inflammatory molecule that mediates tolerance to the gut microbiota, and mutations and/or deficiencies in IL-10 cause severe enterocolitis in mice and humans." (PMID 26580658, 2015). "While Il-10−/− mice can be colonized by C. jejuni, resulting in severe enterocolitis, the loss of IL-10 dramatically alters the murine immune system." (PMID 25033044, 2014).
enterocolitis (continued). "Gene-targeted IL-10 knockout mice (IL-10−/−) and IL-10 receptor 2 deficient mice spontaneously develop an enterocolitis by 2–3 months of age with multifocal inflammatory lesions throughout the gastrointestinal tract." (PMID 24712338, 2014). "We further examined efficacy of GrTP against enterocolitis in IL-10 deficient mice exposed to normal gut microbiota." (PMID 23761791, 2013). "IL-10 deficient mice developed severe enterocolitis as manifested by diarrhea, rectal prolapse, and colonic lesions." (PMID 23761791, 2013). "Animal models have shown that IL-10 deficient knockout mice develop spontaneous enterocolitis and that IL-10 deficiency exacerbates the degree of intestinal inflammation in response to a NEC inducing regimen." (PMID 23472217, 2013). "IL-10 deficient animals tolerated Low and Mid doses of GrTP with significant improvement in their enterocolitis symptoms for the duration of experiment." (PMID 23761791, 2013). "IL-10 deficient animals became moribund on high dose, while tolerated low and Mid doses with significant improved symptoms of enterocolitis." (PMID 23761791, 2013). "Supporting evidence for a role for IL-10 in inflammation is derived from studies in mice deficient in IL-10 or harboring mutated IL-10, which are a model of enterocolitis." (PMID 22681958, 2012). "Because IL-10-deficient mice develop enterocolitis, IL-10 is thought to be involved in maintenance of tolerance to self." (PMID 22321827, 2012). "Classical studies reported that the enterocolitis in IL-10-deficient mice is associated with uncontrolled cytokine production by activated macrophages and CD4+ Th1-like T cells." (PMID 22400037, 2012). "On the other hand, IL-10-deficient mice at 10 weeks of age showed already established enterocolitis with infiltration of leucocytes in the gut mucosa and submucosa areas." (PMID 22400037, 2012). "Additionally, loss-of-function mutations in IL-10 and IL-10R lead to severe infantile enterocolitis resembling CD, characterized by VEO-IBD." (PMID 38137450, 2023). "Mice deficient in IL-10 develop spontaneous enterocolitis, characterised by progressive cellular infiltration of the cecum, colon, rectum, and small intestine, with transmural lesions and a high incidence of colorectal adenocarcinomas observed in 6-month-old mice." (PMID 36012618, 2022). "Mono-colonisation of germfree IL-10-deficient mice with Enterococcus faecalis triggered enterocolitis, with subsequent studies showing distal colitis in Enterococcus faecalis mono-colonised IL-10-deficient mice and a mild cecal inflammation in Escherichia coli mono-colonised animals." (PMID 36012618, 2022). "Administration of Lactobacillus species from birth prevented the development of enterocolitis in IL-10-deficient mice and administration of an 8-strain probiotic to IL-10-deficient mice with established inflammation improved disease by normalising the epithelial barrier." (PMID 36012618, 2022). "In addition, secondary abiotic IL-10−/− mice deficient in the innate receptor nucleotide-oligonucleotide-domain 2 (Nod2) developed less severe enterocolitis upon peroral C. jejuni infection." (PMID 33261211, 2020). "Moreover, the enterocolitis exhibited by IL-10−/− mice has been associated to an uncontrolled Th1 response that leads transmural lesions in aged mice." (PMID 31608070, 2019). "In fact, the results obtained in IL-10−/− mice suggest that the loss of the intestinal homeostasis after CSC exposure can result in a symptomatic enterocolitis with a pathological inflammation in genetically susceptible individuals, as occurs in patients with CD." (PMID 31608070, 2019). "Moreover, our results obtained in mice unable to produce interleukin 10 (IL-10−/− mice) suggest that CSC treatment can induce a symptomatic enterocolitis with a pathological inflammation in genetically susceptible individuals." (PMID 31608070, 2019).
enterocolitis (continued). "In conclusion, this case highlights the importance of early diagnosis of IL-10/IL-10R deficiency in patients with early onset enterocolitis, especially with severe perianal diseases and other clinical features including chronic folliculitis and recurrent respiratory diseases." (PMID 27699073, 2016). "In fact, IL-10- and IL-10 receptor-deficient mice develop spontaneous enterocolitis." (PMID 26608030, 2015). "Enterocolitis was induced in IL-10 deficient mice by exposure to the normal gut microbiota." (PMID 23761791, 2013). "Interestingly, our results suggest that during malnutrition Giardia infection may induce innate IL-10 production, that might partially attenuate inflammatory responses induced by enteropathogens that cause enterocolitis." (PMID 31260452, 2019). "IL-10 is highly associated with IBD, as evidenced by the appearance of spontaneous enterocolitis, as indicated by the emergence of spontaneous enterocolitis in both IL-10-knockout (IL-10-/-) and IL-10-receptor-beta-knockout (IL-10Rβ-/-) mice." (PMID 39201260, 2024). "In a different study using IL-10−/− mice, which develop spontaneous enterocolitis, researchers found that female mice had a shorter colon length and greater levels of IL6 and TGFβ in the colon compared to males." (PMID 38255320, 2024). "This is an important aspect of the CM/exosome action, since IL-10 decrease is linked to IBD; in particular, Il-10 (−/−) mice develop enterocolitis." (PMID 36289619, 2022). "IL-10 knock out mice show an altered microbial composition, and spontaneously develop enterocolitis over time." (PMID 34603258, 2021). "VEOIBD, especially with IL10/IL10R signalling pathway deficiency, is characterized by severe enterocolitis, perianal disease and proctitis involving the colon and terminal ileum." (PMID 31931724, 2020). "In this line, the aim of the present work was to evaluate the L. lactis MG1363 FnBPA+ (pValac:il-10) strain as therapy in IL-10−/− mice and evaluate its capacity to diminish and/or prevent the onset of enterocolitis." (PMID 32703192, 2020). "IL-10 is highly relevant to IBD, as exhibited by the development of spontaneous enterocolitis in both IL-10−/− and IL-10Rβ−/− mice." (PMID 32670290, 2020). "IL-10 is a key mediator of gut homeostasis and IL-10 deficient mice (IL10KO) develop spontaneous enterocolitis in response to resident enteric bacteria." (PMID 31781119, 2019). "IL-10-/- mice is able to develop a slow and progressive enterocolitis under specific pathogen-free (SPF) conditions." (PMID 31509557, 2019). "Interleukin 10 knock out (IL-10KO) mice, which spontaneously develop enterocolitis, showed crypt elongation and aberrant expression of E-cadherin." (PMID 30809073, 2019). "Within 6 days following peroral C. jejuni infection, secondary abiotic IL-10−/− mice develop acute ulcerative enterocolitis mimicking key features of severe campylobacteriosis in humans, with a specific cytokine response." (PMID 31569415, 2019). "Previous reports that support the role of IL-10 receptor-β in the IL-10 receptor complex have shown that IL-10 receptor-β-/- mice developed severe enterocolitis, and the cells from these mice were unresponsive to IL-10 31,34,35." (PMID 26059905, 2015). "It is also evident that IL-10 produced by T cells can inhibit inflammation in the gut and thus the development of severe enterocolitis." (PMID 25437299, 2014). "This study aimed to characterize morphological and immunological alterations in gut mucosa of IL-10−/− at 6, 10, or 16 weeks of ages, covering a period since the onset of symptoms until established enterocolitis." (PMID 22400037, 2012). "Parameter such as onset and severity of enterocolitis in IL-10−/− mice varies according to the animal facility that mice are kept." (PMID 22400037, 2012). "For example, IL-10 knockout mice exhibit a generalized enterocolitis and, in fact, 60% develop colorectal adenocarcinomas by 6 months of age." (PMID 21611205, 2011).
enterocolitis (continued). "Specific pathogen-free IL-10-KO mice acquire gut microbiota as they age, but they never fully develop diverse, commensal microbiota and this appears to be attributable to the spontaneous generation of enterocolitis at the 4–6 weeks of age." (PMID 37942948, 2023). "Axenic, luminal sterile IL-10-deficient adult mice do not develop enterocolitis, while they do, including elevated levels of IFN-gamma in cecal and colonic tissue, after inoculation with intestinal microflora." (PMID 36430939, 2022). "An important role for the gut microbiota in influencing the general enterocolitis seen in IL-10-deficient mice was implicated by a lack of disease in mice housed in specific pathogen-free conditions, or in germ-free conditions." (PMID 36012618, 2022). "Following C. jejuni infection, secondary abiotic NOD2−/− IL-10−/− mice harbored the pathogen at high loads, but developed less severe enterocolitis as compared to IL-10−/− counterparts, indicating that NOD2 signaling increases the severity of campylobacteriosis." (PMID 32231139, 2020). "Secondary abiotic IL-10-/- mice that had been pre-treated with vitamin C or carvacrol, for instance, harbored lower colonic pathogen loads and were suffering from less severe enterocolitis upon C. jejuni infection as compared to placebo control animals." (PMID 32466564, 2020). "Also patients with deleterious mutations in IL10, IL10RA or IL10RB develop severe enterocolitis in the first few months of life." (PMID 33240582, 2020). "IL-10 is a key cytokine that facilitates immune regulation and consequently IL-10-/- mice develop spontaneous enterocolitis associated with the lack of regulatory T cells." (PMID 33664728, 2020). "They described that Il10−/− mice housed in a specific pathogen free environment develop an attenuated disease with lesions restricted to the proximal colon, while Il10−/− mice housed under conventional conditions develop enterocolitis affecting the entire large intestine." (PMID 31396223, 2019). "Moreover, our results help to explain why IL-10-/- mice develop enterocolitis in response to microorganisms." (PMID 31509557, 2019). "Mice with the LysM-Cre driven leukocyte-restricted IL-10 deficiency were shown not to spontaneously develop an enterocolitis." (PMID 30581430, 2018). "Moreover the immune systems of Il-10−/− mice are so sensitive that the presence of any commensal microbe can potentially trigger spontaneous enterocolitis." (PMID 25033044, 2014). "Importantly, gnotobiotic IL-10−/− mice infected with the parental WT strain were severely compromised and developed ulcerative enterocolitis with bloody diarrhea and wasting symptoms, hence mimicking severe campylobacteriosis in immuno-compromised patients." (PMID 24959425, 2014). "However, in the IL-10−/− mice analyzed here the clinical signs of enterocolitis following C. jejuni infection remained rather subtle." (PMID 22563475, 2012). "IL-10 knockout mice spontaneously develop chronic enterocolitis throughout the intestinal tract; early IL-10 administration prevented the development of enterocolitis in these mice, suggesting that IL-10 counterbalances effectors present in intestinal lesions." (PMID 22194981, 2011). "Similarly, IL-10 transgene supplementation was successful in IL10-/- mice, as evidenced by the serum IL-10 level, and significantly reduced index scores of enterocolitis activity, increased weight-to-length colonic ratios, and decreased scores of microscopic inflammation." (PMID 40830617, 2025). "The importance of IL-10 and the intestinal microbiome as a driver of inflammation was initially described by Kuhn and colleagues who discovered spontaneous enterocolitis development in IL-10-deficient mice housed under non-specific-pathogen free (SPF) conditions." (PMID 34421921, 2021).
enterocolitis (continued). "The main reasons for these severe C. jejuni-induced immunopathological responses in the acute stages of enterocolitis in mice are (i) the absence of colonization resistance following microbiota depletion and (ii) the lack of IL-10 enhancing susceptibility of mice to C. jejuni LOS." (PMID 31936044, 2020). "This animal infection model was chosen since within one week upon C. jejuni infection gnotobiotic IL-10-/- mice harbored high pathogenic loads and displayed non-selflimiting acute symptoms of infection-induced enterocolitis such as bloody diarrhea and wasting syndrome." (PMID 26406497, 2015). "Acute C. jejuni B2 induced enterocolitis was further confirmed by distinct histopathological changes of the colonic mucosa as indicated by significantly higher histopathological scores in C. jejuni B2 infected as compared to naive and E. coli infected gnotobiotic IL-10−/− mice." (PMID 22808254, 2012). "We demonstrated that 10% raw broccoli sprouts in the diet of IL-10-KO mice induced increased bacterial richness, SFN in the plasma, and collectively reduced the symptoms of enterocolitis." (PMID 37942948, 2023). "The absence of IL-10 and IL-10R results in severe enterocolitis that manifests early in development." (PMID 39458516, 2024). "Although we do not know the consequences of reduced IL10 in the absence of inflammation in the airway, targeted disruption of IL10 in mice produces spontaneous enterocolitis." (PMID 33580593, 2021). "When born and maintained in GF conditions, Il10−/− mice do not develop the spontaneous enterocolitis typical of the model, and similar effects have been observed when Il10−/− mice are treated with antibiotics since neonatal age." (PMID 33572538, 2021). "The lack of the immunosuppressive effects mediated by interleukin-10 leads to a progressive enterocolitis related to the continuous stimulation of the mucosal immune system by the microbiota." (PMID 31275292, 2019). "From these analyses it was possible to observe that at the time of the study IL-10-/- mice did not present enterocolitis or more signs of ileum inflammation than WT mice." (PMID 31509557, 2019). "Considering that enterocolitis does not occur if IL-10-/- mice are in germ-free conditions, it is possible that inflammation depends on an altered interaction between the microbiota and the immune response." (PMID 31509557, 2019). "Upon peroral C. jejuni infection gnotobiotic IL-10−/− mice develop non-selflimiting ulcerative enterocolitis within one week p.i. mimicking severe campylobacteriosis in immuno-compromized patients." (PMID 24587249, 2014). "Interleukin 10’s interest in the attempt of developing an efficient therapy against IBD has grown since it was observed that IL-10 knockout (IL-10−/−) mice develop spontaneous enterocolitis when not maintained in germ-free conditions." (PMID 25106058, 2014). "In addition, the discovery that mice lacking IL-10 and IL-10 receptor expression develop spontaneous enterocolitis established the crucial role of IL-10 in intestinal inflammation and in the etiology of IBD24." (PMID 35411016, 2022). "Germ‐free or antibiotics‐treated IL‐10−/− mice, however, neither develop enterocolitis nor tumors." (PMID 32350866, 2020). "In our prior studies of IL-10-/- mice demonstrating elevated ENO values, the mice that were observed with symptoms of rectal prolapse, diarrhea, and failure to gain weight, were routinely excluded from consideration, due to the tendency of IL-10-/- mice to develop enterocolitis with age." (PMID 18505586, 2008). "Interestingly, these cells have not yet been characterized in IL-10-/- mice, so their contribution to the enterocolitis developed by these mice is still unknown." (PMID 31509557, 2019).